RN7SKP199 (RN7SK pseudogene 199)
Gene: Miscellaneous RNA gene on chromosome 4 (45,995,119 to 45,995,423, forward strand). Ensembl gene ENSG00000222257.
Homologues: Orthologues: chimpanzee 7SK (92% identical), guinea pig 7SK (68% identical), mouse Gm56283 (61% identical). Paralogues in human: RN7SKP255 (74% identical), 7SK (74% identical), RN7SKP71 (74% identical), RN7SKP79 (74% identical), RN7SKP180 (73% identical), RN7SKP211 (73% identical), RN7SKP246 (73% identical), RN7SKP45 (73% identical), RN7SKP243 (73% identical), RN7SKP171 (72% identical), RN7SKP176 (72% identical), RN7SKP203 (72% identical), and 284 more.